CTNNB1 (catenin beta 1)
Diseases named in the same sentence as CTNNB1 in open-access papers (continued):
Sharing a sentence is not in itself a finding about the gene and the disease.
gastric cancer (continued). "Our analysis identified hsa-miR-9-3p and hsa-miR-9-5p as shared regulators of COL4A1, CTNNB1, THBS2, and E2F3, a pattern that aligns partially with earlier studies reporting dysregulation of the miR-9 family in gastric cancer." (PMID 41291892, 2025). "Protein-level validation using immunohistochemistry (IHC) data from the HPA database revealed that THBS2, CTNNB1, COL4A1, and E2F3 exhibited markedly higher staining intensity in gastric cancer tissues compared to normal gastric mucosa." (PMID 41291892, 2025). "In our study, TNF, IL6, BCL2, PTEN, CTNNB1, and SRC are presented as common target genes between gastric cancer and AMK." (PMID 38612999, 2024). "The literature research revealed that, in a mouse model of gastric cancer, Myosin IIA in cancer cells can form complexes with other molecules and bind to the promoter region of the Ctnnb1 gene to mediate its transcriptional expression." (PMID 39404399, 2024). "Myosin heavy chain 9 (MYH9) has also been found to promote the transcription of catenin beta 1 (CTNNB1), thus rendering resistance to gastric cancer cells against anoikis both in vivo and in vitro." (PMID 35359956, 2022). "EpCAM expression was positively correlated with the expression of CTNNB1 in LUAD, COAD, ESCA, LUSC, and stomach cancer." (PMID 34790117, 2021). "In many previous studies, gene signatures were ever identified when analyzing expressions in residual gastric cancer cells after neoadjuvant chemotherapy, composing of GSK3B, the β-catenin gene CTNNB1, NOTCH2 and many other genes." (PMID 29088749, 2017). "Our study analysing the expression of CSC related genes in residual gastric cancer cells after neoadjuvant chemotherapy identified a gene signature with a high prognostic impact composed of GSK3B, the β-catenin gene CTNNB1 and NOTCH2." (PMID 22970250, 2012). "These possibilities point toward a future in which molecularly informed treatment plans, centered on targets such as CTNNB1 and COL4A1, may offer improved outcomes for patients with H. pylori–related gastric cancer." (PMID 41291892, 2025). "Circ_SMAD4 promotes gastric cancer tumorigenesis by recruiting TCF4 to facilitate CTNNB1 transcription in the nucleus and sequestering miR-1276 in the cytoplasm to prevent the silencing of CTNNB1 mRNA, thereby activating the Wnt/β-catenin pathway." (PMID 40708910, 2025). "Our study illustrated long non-coding RNA MIR137HG could promote the progression of gastric cancer through interacting with FUS and affecting a series of its downstream molecules (MET, RHOC, and CTNNB1." (PMID 35733138, 2022). "Meanwhile, a gastric cancer cell line HGC27 which harbors only a PIK3CA mutation and two other gastric cancer cell lines SNU16 and SNU5 lacking PIK3CA and CTNNB1 mutations were used to test the specificity of synergistic effects of copanlisib and mebendazole." (PMID 34493320, 2021). "Moreover, recent resistance profiling in gastric cancer has suggested that Wnt beta catenin activation and ECM remodeling cooperate to generate a drug tolerant state, which aligns with our findings for CTNNB1 and COL4A1." (PMID 41291892, 2025).
adenoma (73 papers, 2008 to 2026). A neoplasm arising from the epithelium. "As in other adrenocortical tumors such as adrenocortical carcinoma and cortisol-producing adenoma, somatic activating mutations in exon 3 of the CTNNB1 gene, that encodes β-catenin, have also been identified in 2-5% of APA." (PMID 38505749, 2024). "The high mutation frequency of CTNNB1 in adenomas suggests its early driving function in CRA development, although oncogenic mutations in CTNNB1 alone appear insufficient to initiate CRC tumorigenesis." (PMID 39554798, 2024). "To note, in adenomas, the mutational status significantly affected the myeloid cluster, which was highly enriched in CTNNB1‐mutated adenomas." (PMID 39167619, 2024). "Apart from these classic subtypes, mixed variants can be seen, for example, the mixed inflammatory and β-catenin–mutated adenomas, which appear inflammatory on histology but also carry the CTNNB1 mutation." (PMID 39470338, 2024). "While several studies reported a relatively high incidence of aldosterone response to GnRH or LH in vivo, less than 10% mutations of CTNNB1 have been reported in unselected aldosterone-producing adenomas." (PMID 36926028, 2023). "In their study, primary zona glomerulosa-like adenoma cells transiently transfected with the CTNNB1 mutations found in the patients induced the expression of LHCGR." (PMID 36926028, 2023). "More recently, overexpression of LHCGR required combined mutations of GNA11 and GNAQ in CTNNB1-mutant aldosterone-producing adenomas presenting in puberty, pregnancy or menopause." (PMID 36926028, 2023). "Somatic mutations in CTNNB1 have been identified in around 3% of sporadic APAs and have been associated with female gender and relatively large adenomas." (PMID 34829937, 2021). "Adenomas with CTNNB1 mutations showed a large number of differentially expressed genes (1360 compared to 106 and 75 for KCNJ5 and ATP1A1/ATP2B3 respectively) and clustered together in a hierarchical clustering analysis." (PMID 31000732, 2019). "Aldosterone-producing adenomas with CTNNB1 mutations have been reported to have higher CYP11B2 mRNA and protein (by immunohistochemistry) expression levels compared to those harboring KCNJ5 mutations." (PMID 29594118, 2018). "Adenomas from APCMin/+ mice are characterized by the increased expression of Serpine 2, in comparison with adenomas with CTNNB1 mutations." (PMID 29652830, 2018). "Mutations in CTNNB1 have also been described in glucocorticoid-producing adrenal cortical proliferations including adenomas." (PMID 29594118, 2018). "LHCGR was diffusely expressed in adrenal tissues and was prominent in adenoma harboring CTNNB1 mutations." (PMID 28102204, 2017). "GnRHR showed diffuse cytoplasmic, membranous and nuclear expressions on adenomas, and was especially enhanced in adenoma harboring CTNNB1 mutations from female patients." (PMID 28102204, 2017). "Adenoma harboring CTNNB1 mutations displayed heterogeneous cytoplasmic, membranous and nuclear expression of active β–catenin." (PMID 28102204, 2017). "CYP11B2 expressed diffusely on adenomas harboring CTNNB1 mutations and showed mottled staining on adenomas harboring KCNJ5 mutations." (PMID 28102204, 2017). "Targeted sequencing for the reported mutations in APAs of KCNJ5, CACNA1D, ATP1A1, ATP2B3 and CTNNB1 exons was performed from the adenomas." (PMID 28102204, 2017). "About 3.7% (8 adenomas) of our 219 APA patients were found to harbor somatic CTNNB1 mutations, and their molecular expressions and clinical outcomes were reported." (PMID 28102204, 2017). "Tumors with CTNNB1 mutations were associated with relatively large adenomas, and were found both in female and male patients, however with a small overrepresentation in females." (PMID 26815163, 2016).
adenoma (continued). "One polypoid and one flat adenoma harbored a CTNNB1 mutation, both at the same nucleotide position c.134C>T (p.S45F) and both adenomas contained no APC truncating mutation." (PMID 22848674, 2012). "Another major cause of cortisol-producing adenomas is mutations in CTNNB1, the gene for β-catenin." (PMID 41511347, 2025). "All 3 feline tumors harboring CTNNB1 mutations were classified as adenomas." (PMID 39429164, 2024). "Three somatic mutations were identified using targeted Sanger sequencing at residues in the same genes, but distinct from the amino acid residues identified by WGS, including 2 further CTNNB1 mutations at p.S45P and p.S37Y in cases 11 and 13, respectively, both of which were in adenomas." (PMID 39429164, 2024). "Moreover, we have used Sanger sequencing to confirm that there were no other conventional and well-characterized aldosterone-driving gene mutations, including KCNJ5, ATP1A1, CACNA1D, and CTNNB1, in the adenoma harboring with ATP2B3 K416_F418delinsN mutation." (PMID 34572956, 2021). "In our cohort, 5 of the 11 patients harbored CTNNB1 mutations; in 4 of these 5 cases, GBC and its adjacent LG-BilIN shared the same mutations in CTNNB1, suggesting that CTNNB1 mutations play a more active role in the formation of carcinoma in the context of adenoma/dysplasia than GBC alone." (PMID 34362903, 2021). "Therefore it is possible that hetero- and homozygously CTNNB1 mutated adenomas are at low risk to transform into cancer unless they acquire DNA mismatch repair deficiency as just the right mechanism to switch to malignancy." (PMID 33115416, 2020). "Somatic mutations of CTNNB1 have been associated to female gender and relatively large adenomas." (PMID 32783015, 2020). "APC is the gene most frequently mutated in conventional colon adenomas; four genes recurrently mutated in adenomas CTNNB1 (catenin-β1), KRTAP4-5 (keratin-associated protein 4–5), GOLGA8B (golgin A8 family member B) and TMPRSS13 (transmembrane protease, serine 13) had the oncogene pattern." (PMID 29652830, 2018). "CTNNB1 mutations occur in cortisol producing adenomas (CPA)." (PMID 26815163, 2016). "If adenoma to carcinoma sequences does occur, one could speculate that patients with tumors harboring CTNNB1 mutation have a small but increased risk of malignant transformation." (PMID 26815163, 2016). "In the normal population, it is postulated that most CRCs arise through biallelic somatic APC mutations initiating an adenoma that may develop into a carcinoma as a result of acquiring additional driver mutations, and less often through an initiating mutation in CTNNB1." (PMID 38741120, 2024). "Since we observed a CTNNB1 mutation frequency of 7.3% in adenomas from Swedish patients, this may suggest possible contribution of geographical origin (dietary or environmental differences, or different genetic backgrounds) to mechanisms of parathyroid disease." (PMID 18541010, 2008). "Within T-DNA, somatic variants were identified in 53% of adenomas: PRKACA in 2/7 CPA-CS, CTNNB1 in 3/5 CPA-MACS and 1/7 CPA-CS, KCNJ5 in 2/5 APA and CACNA1D in 1/5 APA." (PMID 39891827, 2025). "Lin and colleagues characterized the mutational alterations using WES and proposed four genes (CTNNB1, KRTAP4-5, GOLGA8B, and TMPRSS13) as the potential somatic drivers in conventional adenomas." (PMID 40757636, 2025). "In the Apcmin/+ model, supplementation with KLK1 significantly inhibited adenoma formation, reduced epithelial dysplasia, and downregulated pro‐oncogenes such as Mmp2, Mmp9, Fap, Dcn, and Ctnnb1." (PMID 40859429, 2025).
adenoma (continued). "Double somatic mutations in CTNNB1 and GNA11/Q have recently been identified in a small subset of aldosterone-producing adenomas (APAs)." (PMID 38505749, 2024). "This does not conflict with the firmly established role of β-catenin in colonic neoplasia; indeed, CTNNB1/β-catenin overexpression in mouse colonic epithelial cells induces adenomas and Ctnnb1 knockout blocks adenoma formation in Apc mutant mice." (PMID 37759479, 2023). "Alterations in the Wnt pathway are an initial event in the adenoma-carcinoma progression, predominantly due to mutations in the APC (40.3% to 80.0%) followed by the CTNNB1 gene (11.9–20.0%)." (PMID 35761395, 2022). "For example, a recent study analyzed gene expressions in cortisol-producing adenomas (CPA) with PRKACA mutation and compared to GNAS and CTNNB1 mutant CPAs." (PMID 36105398, 2022). "Mutations in the Wnt-related genes CTNNB1, EP300, TCF7L2, and the AMER1 genes were also observed, but at a lower frequency, in accordance with previous data on adenomas with high grade dysplasia." (PMID 33923068, 2021). "Previous studies reported that adenoma or LG-BilIN expresses significantly higher β-catenin than GBC, and 62.5% of LG-BilIN samples harbored mutations in CTNNB1 exon 3, but this rate was only 4.8% in the GBC39,40." (PMID 34362903, 2021). "Several somatic mutations have been found in aldosterone-producing adenomas in KCNJ5, ATP1A1, ATP2B3, CACNA1D, and CTNNB1 genes." (PMID 32783015, 2020). "As expected, we found that APC was the most frequently mutated gene across the adenomas studied, while other WNT pathway genes (CTNNB1, EP300, TCF7L2, and AMER1) were altered less frequently." (PMID 31781186, 2019). "Eleven somatic mutations were located in genes involved in the early adenoma formation (APC, RNF43 and CTNNB1), whereas two mutations were detected in genes involved in later stages (ARID1A, NRAS)." (PMID 31285513, 2019). "CTNNB1-mutant aldosterone-producing adenomas appear more prevalent in female and older patients with a shorter duration of hypertension." (PMID 29594118, 2018). "In a cohort of PRKACA-wild-type adenomas, glucocorticoid-producing CTNNB1-mutant adrenocortical adenomas were more likely to present with subclinical Cushing syndrome." (PMID 29594118, 2018). "Sequencing studies showed that LS-associated MMR-deficient adenomas display a lower frequency of APC or CTNNB1 mutations (37%), compared to that observed in LS-associated MMR-proficient adenomas (72%) or in sporadic adenomas." (PMID 29652830, 2018). "Adenomas with mutant CTNNB1 and all investigated adenomas revealed an unremarkable expression of GATA4." (PMID 28102204, 2017). "The CTNNB1 mutants displayed higher, diffuse active β–catenin expression than KCNJ5 mutation carriers or WT, especially in adenomas from female patients; and showed prominent nuclear staining." (PMID 28102204, 2017). "The results of mRNA expression from real-time PCR showed that CTNNB1 mutated adenoma had similar density of CYP11B2 expression as WT patients; however, both groups of adenoma had less CYP11B2 expression than those with KCNJ5 mutations (all p < 0.01)." (PMID 28102204, 2017). "Regarding CTNNB1, three adenomas carried the codon 41 ACC→GCC mutation and two adenomas exhibited the codon 45 TCT→TTT mutation." (PMID 24212608, 2010). "The molecular driver of the adenoma causing MACS may involve somatic mutations, such as in CTNNB1 (β-catenin), which could disrupt cellular regulation and promote autonomous cortisol secretion." (PMID 41424912, 2026).
adenoma (continued). "CTNNB1 alterations also drive aldosterone-producing adenomas and hyperplasia of the adrenal cortex and recent work has demonstrated that disrupting fibroblast growth factor signaling in these cells may offer therapeutic benefit." (PMID 41511347, 2025). "This hypothesis relies on mechanistic differences in adenoma formation in MLH1 carcinogenesis through inactivation of CTNNB1, and a lower incidence of adenomas in these carriers." (PMID 39066849, 2024). "Somatic variants in CTNNB1 gene, encoding β-catenin, have been identified in 2-5% of patients with sporadic APA; similarly, to APAs due to KCNJ5 variants, these APAs are associated with larger adenomas and are more commonly seen in females." (PMID 36105398, 2022). "Adenomas in patients with PMS2-associated CRCs do not exhibit CTNNB1 mutations; consequently, those carriers have a lower CRC risk." (PMID 36553592, 2022). "This is notable since LS colorectal tumorigenesis is generally thought to follow the classic adenoma-carcinoma sequence, whereby MMRd is a late event in adenomas, with established Wnt signaling activation due to somatic APC, CTNNB1 or RNF43 PVs, that causes rapid progression to carcinoma." (PMID 36291559, 2022). "Although APC and CTNNB1 mutations are major causes of WNT/β-catenin signaling activation in conventional-type adenomas, these genetic alterations are absent in SSA/Ps." (PMID 30458818, 2018). "This is also consistent with the finding that larger non-functional adenomas are frequently associated with CTNNB1 mutations." (PMID 29594118, 2018). "This study does not assign a single specific signaling mechanism by which loss of PKD1 inhibits CRC, although it excludes inhibition of WNT/CTNNB1 as one possibility, based on elevation of this pathway in Pkd1-mutated murine adenomas or in human tumors bearing somatic PKD1 mutations." (PMID 37542051, 2023). "In addition, patients with PMS2 germline mutations had a lower CRC risk, a high frequency of MMR-P adenomas and were negative for CTNNB1 somatic mutations." (PMID 33923068, 2021). "Activating somatic mutations in the CTNNB1 gene have been reported at a similar prevalence in both APAs (27% of 26 tumors, with a higher proportion in nonfunctioning adenomas compared with cortisol-producing adenomas) and malignant adrenocortical tumors (31% of 13 adrenocortical carcinomas)." (PMID 34829937, 2021). "CTNNB1 was mutated in 12.2% of the adenomas, but not in serrated lesions." (PMID 24212608, 2010). "Conversely, no concomitant CTNNB1, PRKACA, PRKAR1A or GNAS somatic variant (classically met in cortisol-producing adenomas) with a germline ARMC5 alteration has been yet reported to our knowledge." (PMID 39910635, 2025). "By contrast, MMR-P adenomas had a higher frequency of APC and CTNNB1 somatic mutations, but no RNF43 somatic mutations." (PMID 33923068, 2021). "In a single adenoma, three genes (APC, K-Ras and CTNNB1) were found to be altered." (PMID 24212608, 2010). "CRCs arising by the CTNNB1 pathway appear to have no sojourn time as adenomas, are not frequent in path_MMR carriers, and may be specific for path_MLH1 carriers." (PMID 38741120, 2024). "However, overexpression of RAC1B did not increase the number of proliferative cells in the normal small intestine nor in the early adenomas and did not increase the expression of canonical Wnt target genes such as Axin2, Tcf7, Lef1 or Ctnnb1." (PMID 34564693, 2021). "Interestingly, we did not detect a change in mRNA or protein levels of Ctnnb1 (β-catenin) in ApcMin adenomas, suggesting that Ap4 directly regulates Wnt/β-catenin target genes." (PMID 30177706, 2018).
adenoma (continued). "CTNNB1 activation was frequently observed in both intermediate- and low-methylation epigenotypes without statistical significance (P = 0.1), and its frequency did not increase from adenoma to cancer (P = 0.8)." (PMID 27563825, 2016). "CTNNB1 was altered in 12% of the adenomas, but not in serrated lesions." (PMID 24212608, 2010).